EPCAM (epithelial cell adhesion molecule)
Diseases named in the same sentence as EPCAM in open-access papers (continued):
Sharing a sentence is not in itself a finding about the gene and the disease.
tumor (continued). "Cancer stem cells expressing EpCAM are more tumorigenic than EpCAM-negative stem cells and, due to their resistance to radiation and chemotherapy, targeting EpCAM might be a promising approach to impede tumor recurrence after chemo- or radiotherapy." (PMID 23110550, 2012). "However, the fact that the majority of cancers expressed EpCAM in vivo and our results indicate that EpCAM expression in tumours is not a limiting factor for its usage for specific targeting." (PMID 22590529, 2012). "The greater presence of CD133 and EpCAM positive cells in the post-TACE samples could result either because this cell population selectively survived treatment, or because recurrent tumor growth resulted in a dedifferentiation process that generated positive cells." (PMID 23216644, 2012). "Finally, EpCAM expression in the primary tumour did not correlate with EpCAM positivity in the preoperative peritoneal lavage fluid (data not shown)." (PMID 21281486, 2011). "This strategy also presents one limitation, however; by using anti-EpCAM and anti-ErbB2 Micro Beads for immunoselection, tumour cells that do not express or express low levels of EpCam or HER2 may not be enriched." (PMID 21672237, 2011). "In this study we report a platform that can be used to simultaneously capture multiple circulating tumor cell types by employing mixtures of antibodies that may include, but are not solely dependent on, EpCAM." (PMID 21577258, 2011). "We then speculated that the EpCAM positive but epithelial transcript negative cells isolated from the SLNs could be tumor derived cells passing through an epithelial to mesenchymal transition (EMT)." (PMID 21816090, 2011). "When we investigated gene expression using other RT-PCR markers we found expression profiles consistent with the EpCAM positive but epithelial transcript negative cells (EpCAM+/hMAM-) being tumor derived cells passing through an epithelial to mesenchymal transition (EMT)." (PMID 21816090, 2011). "Interestingly, our observation that the CpGs located around −230 within the Sp1 binding sites were methylated in EpCAM-negative ovarian cell lines and unmethylated in the EpCAM-positive lines was also reported for several other types of tumours." (PMID 21694727, 2011). "Clarke's group used similar xenograft techniques to show that CD44+/CD166+/EpCAMHigh cells isolated from human CRC could also establish a phenocopied tumor while no growth was observed with CD44-/CD166-/EpCAM Low cells." (PMID 21318087, 2011). "Finally, EpCAM expression in the primary tumour did not correlate with EpCAM positivity in preoperative blood (data not shown)." (PMID 21281486, 2011). "However, none of the previous trials have analyzed EpCAM expression in tumor tissues, prospectively or retrospectively." (PMID 21152431, 2010). "To compensate for low or no expression of EpCAM and CK, we also developed an assay with a combination of anti-CK and anti-EpCAM antibodies that allows the enrichment of all types of CTCs including CK+&EpCAM+, CK+&EpCAM-/low and CK-/low&EpCAM+ tumor cells." (PMID 18687126, 2008). "CK-&EpCAM- tumor cells are not discussed in this enrichment and detection study." (PMID 18687126, 2008). "Therefore, we used serial tumour sections and stained for CD133, CK20, and EpCAM." (PMID 18781171, 2008). "Those tumor cells that express CK but with low or no EpCAM, or vice versa, may not be enriched by anti-EpCAM antibody." (PMID 18687126, 2008). "Epithelial cell adhesion molecule (Ep-CAM; CD326) is used as a target by many immunotherapeutic approaches, but little data are available about Ep-CAM expression in major human malignancies with respect to level, frequency, tumour stage, grade, histologic tumour type and impact on survival." (PMID 16404366, 2006). "Hence, we speculated that the dominant expression of HVEM in CD45−EpCAM+ cancer cells but not in CD45+EpCAM− immune cells in the tumor of OvCa widely exists in different types of epithelial OvCas." (PMID 40105652, 2025).
tumor (continued). "Our findings suggest that TSD+ CSCs, a subpopulation of EpCAM+/ABCG2+ CSCs, might engage in a form of self-sacrifice to protect the R-CSC, a pool of dormant CSC population capable of reawakening upon encountering future cisplatin-induced stress and resuming tumor growth." (PMID 39963656, 2024). "Additionally, a limitation of our study was that we did not identify tumor cells in a more specific manner, such as sorting or staining EpCAM+ cells, which could be improved in future studies." (PMID 38600469, 2024). "Moreover, EpCAM-CAR-T cells were used to kill EpCAM-positive and negative tumour cells in vitro." (PMID 39107717, 2024). "Moreover, we observed a reduction in the percentage of epithelial (i.e., EpCAM+) cells within the tumor, and a significant decrease in the percentages of CD133+ and CD133+/CXCR4+ cells within the EpCAM+ cell population, which is in line with our hypothesis that Ru1 affects the CSC compartment." (PMID 38281027, 2024). "Since the epithelial-mesenchymal transition is a critical component of tumor invasion and metastasis, the shed GC cells may lose epithelial markers, which is why the positive expression of EpCAM is not high in PLF FCCs (6%)." (PMID 38952968, 2024). "As per our working hypothesis, we expect all EpCAM+/ABCG2+ CSCs to exhibit altruistic behavior when exposed to a serum-free and hypoxic microenvironment that mimics the stressful microenvironment of intermittent hypoxia and oxidative stress prevalent in the tumor." (PMID 39963656, 2024). "Additionally, platinum-based chemotherapeutic agents preferentially eliminate EpCAM-negative OC cells, suggesting that the remaining EpCAM-positive cells may contribute to tumor recurrence after chemotherapy." (PMID 37509310, 2023). "Notably, we found that the ductal cell markers and epithelial cell-specific markers reported previously, such as EPCAM, KRT18, SOX9, KRT19, MUC1, and FXYD3, were commonly expressed in the majority of clusters except for cluster 17, confirming tumor cell identity." (PMID 37324492, 2023). "Since we did not have the confocal images, we could identify the plasma-membrane EpCAM positivity of a tumor cell depending on the orientation of the cell on the microfilter as shown in HCC1975 and NCI-H441 cells using the DAPI/CK-FITC/EpCAM-PE/CD45-Cy5 antibodies." (PMID 35740537, 2022). "Furthermore, tumor markers such as FGF21 and EPCAM are lowered following UGCG OE, which could be related to glucosylceramide (GlcCer) and lactosylceramide (LacCer) accumulation in glycosphingolipid-enriched microdomains (GEMs) and subsequently altered signaling protein phosphorylation." (PMID 34626204, 2021). "Importantly, Dox‐treated EpCAM−/CD133− nonstem cells had increased in vivo tumor‐forming ability." (PMID 33524223, 2021). "Indeed, a few tumor fragments were EpCAM-negative and required additional visual verification." (PMID 34834440, 2021). "However, EpCAM-dependent methods may not be applicable to the isolation of non-epithelial tumor cells, and CTCs in MPM have not been fully investigated so far." (PMID 34025789, 2021). "Therefore, the EpCAM-based strategies cannot enrich those EpCAM− tumor cells from the peripheral blood, which may not recapitulate the complexity of CTCs and need to be revisited in the future." (PMID 33143160, 2020). "Therefore, tumor cells that express CK but low or no EpCAM may not be enriched by anti-EpCAM antibodies." (PMID 32197486, 2020). "Epithelial–mesenchymal transition (EMT) plays a critical role in promoting migration and invasion of stationary tumor cells and results in down-regulated expression of epithelial markers, which might lead to false-negative findings with epithelial cell adhesion molecule (EpCAM)-based detection." (PMID 30606259, 2019).
tumor (continued). "It is conceivable that the isolation and characterization of CTC discarded by CellSearch®, due to the low expression of EpCAM, might reveal an unexpected clinical significance especially in those tumor types where CTC enumeration has never been validated for prognostic and predictive purpose." (PMID 31636732, 2019). "However, in our in vivo analysis using a mouse xenograft tumor model, decreased volume of the tumors was observed in all the mice treated with irradiation, regardless of whether they were treated with the EpCAM APC or the negative control." (PMID 30140380, 2018). "Additionally, some studies have shown that metastatic lesions have higher expression levels of EpCAM than the primary tumours, suggesting that these antibodies might target these secondary lesions rather than showing any benefit to the primary tumour." (PMID 29329202, 2018). "Since the enumeration of CTCs solely based on EpCAM expression (or that of other epithelial markers like cytokeratins) may not be sufficient for unequivocal identification of cancer cells due to EMT, downstream analysis becomes important for defining truly tumor-derived cells." (PMID 29156783, 2017). "However, it has been reported that EpCAM is highly heterogeneously and dynamically expressed on many types of epithelial tumor cells, and epithelial-mesenchymal transition (EMT) may decrease the expressions of EpCAM and CKs and thus leads to the failure of CTC detection." (PMID 28187533, 2017). "Thus, the EpCAM status of tumour tissue does not necessarily predict the EpCAM status in CTCs." (PMID 27302574, 2016). "Moreover, EpCAM is not uniformly expressed in all tumor types and may not provide the best target for human cancer cell selection." (PMID 27611664, 2016). "Moreover, as a label-dependent approach, the Cellsearch® might have underestimated actual CTC load in circulation owing to the possible existence of EpCAM negative tumor cells." (PMID 27465596, 2016). "It must be recognised that whatever method of detecting CPCs impose limitation on detection, and/or the biomarker selected to detect CPCs may not be capable of detecting all tumour cells, as has been reported with the use of Epithelial Cell Anchor Molecule (EpCAM)." (PMID 27610197, 2016). "However, when using this additional step for isolation of EpCAM positive epithelial tumor cells, one must take into account that tumor cells that do not express EpCAM or express EpCAM at very low levels will be excluded, thus potentially losing important sub-clones of tumor cells." (PMID 24860781, 2014). "Importantly, loss of membranous EpCAM coincided with increasing cytoplasmic staining at the tumour front (detected by polyclonal antibody), suggesting altered cellular localisation due to abnormal post-translational processing of EpCAM rather than reduced expression of this antigen." (PMID 21339979, 2010). "Indeed, EpCAM-targeted immunotherapy may be more effective in the context of established tumours or metastases as opposed to fluid-borne disease." (PMID 17325709, 2007). "Although normal cell expression is also found for other ‘tumour-associated’ antigens being used as antibody or vaccination targets, including HER-2, EGFR, CEA, MUC-1, CD20, CD52 and CD33, this circumstance has in no other case irritated researchers to the extent EpCAM's expression did." (PMID 17211480, 2007). "First, although EpCAM was found to be a reliable marker for tumor cells in blood, malignant ascites, and MPE, there are cases in which it fails to identify tumor cells." (PMID 40525275, 2025). "Importantly, EGFR and EpCAM exhibited no detectable signal in BM samples alone, highlighting their high specificity for cancer cells and demonstrating the sensitivity of our nested qPCR approach, particularly when 5 or more tumor cells were spiked into the sample." (PMID 40073025, 2025).
tumor (continued). "Subsequent analysis of cell surface markers EpCAM (tumor cell marker) and CD45 (immune cell marker) revealed that all tumor cell lines lacked CD45 expression, as expected in pure tumor cell cultures." (PMID 41154384, 2025). "For instance, solitomab, an EPCAM × CD3 bsAbs, showed > 95% of G3 TRAEs due to off-tumor toxicity due to EPCAM expression in non-tumor tissues." (PMID 40508202, 2025). "Tumor and matched adjacent noncancerous tissues were collected and analyzed for the expression of CD44, CD90, CD133, and EpCAM using immunohistochemistry (IHC)." (PMID 40791212, 2025). "Although EpCAM is a CSC marker, we currently do not clearly understand the relationship between CSCs and circulating tumor cells." (PMID 40869256, 2025). "Although EpCAM, PIGR, OLFM4, and CLDN4 have been previously identified as membrane markers for GC, they did not effectively discriminate between HM and tumor tissue in our patient cohort." (PMID 40868067, 2025). "EpCAM-directed CAR-T cells effectively accumulate in tumors in the brain metastasis model, reducing tumor growth without the central nervous system or systemic toxicity." (PMID 41375062, 2025). "This trend was also observed with an increasing number of noncanonical EpCAM- and CD45-positive CTCs (double positive CTCs), whose presence has been described in different tumor types, but their role is not yet fully elucidated." (PMID 38391950, 2024). "In one out of eight animals (12.5%), the injection of EpCAM/GFPCAR T-cell resulted in a complete regression of the tumor and no visible tumor was observed in the in vivo imaging from day 4 until the end of the experiment." (PMID 39358663, 2024). "Most nonimmune cells in iCCA tumors were epithelial-derived tumor cells with high expression of KRT19 and EPCAM." (PMID 38245530, 2024). "Immunohistochemical (IHC) staining revealed that p63 and calponin were negative in tumor cells, while ESA (EPCAM) and c-Kit (CD117) were diffusely but patchy positive." (PMID 39451738, 2024). "We identified a negative correlation between tumor cells that were non-stem by CD44/CD24 but stem by CD133 and those that were CD44+CD24−CD133− in EpCAM-negative CTCs (r = −0.69, p = 0.024)." (PMID 39456890, 2024). "Interestedly, no matter which marker had been used, positively stained tumor cells were rare to see, while CK18-positive cells seem to be more common than EpCAM-positive cells." (PMID 39125505, 2024). "In contrast, mice treated with EpCAM/GFPCAR T-cell demonstrated a reduced growth rate, and none of the animals (0/8) reached a tumor size greater than 1 mm2." (PMID 39358663, 2024). "Those with EpCAM-negative and AFP-negative HCC are usually older but in earlier tumor-node-metastasis (TNM) stages." (PMID 36674932, 2023). "The pan-tumor panel identified nine tumor cell subsets, which were defined as being negative for CD45 and CD56, but expressing at least one of the three markers, namely, EpCAM, FOLR1, and CD24." (PMID 37894472, 2023). "Our data indicate that EpCAM low-expressing CTCs could be used as a valuable tumour surrogate material—although they may be prognostically less relevant than EpCAM high-expressing CTCs—and have particular benefit if no CTCs are detected using EpCAM-dependent technologies." (PMID 36823365, 2023). "In mouse and human solid tumor models, these synNotch CAR-T cells selectively killed EpCAM+ ROR1+ or B7-H3+ ROR1+ tumors cells but not killed EpCAM−ROR1+ cells or B7-H3−ROR1+ cells in normal tissues, resulting in tumor regression without toxicity." (PMID 37131214, 2023). "Substitution of Tyr with Phe (Y6F) which also has a benzyl side chain did not reduce affinity to EpCAM and the cytolytic activity of Y6F CAR-T cells was similar to that of UBS54 CAR-T cells against tumor targets and primary EpC." (PMID 37045815, 2023).
tumor (continued). "On the other hand, even though these negative immunoselection-based techniques can collect CTCs without the use of tumor-specific antigens, the subsequent CTC identification step still depends on common tumor-specific antigens (e.g., EpCAM or CKs)." (PMID 38001632, 2023). "However, since they mainly represent similar genomic clones of the tumour as EpCAM high-expressing CTCs, they could equally act as a tumour surrogate material and could especially be of relevant value if no CTCs are detected with EpCAM-dependent technologies." (PMID 36823365, 2023). "The group treated with non-conjugated nanocarriers showed lower expression of CD133 and EpCAM and no expression of CD44 cells in tumor." (PMID 37149607, 2023). "However, it was suggested that, even if EpCAM low-expressing CTCs may be prognostically less relevant than EpCAM high-expressing CTCs, they could be used as a valuable tumour surrogate material and may have particular benefit if no CTCs are detected using EpCAM-dependent technologies." (PMID 37046848, 2023). "While the non-selective ADAM10 mAb 4A11 bound to both normal colon and tumour epithelial (CD45 negative, EpCam positive) cells, 8C7 preferentially bound to tumour cells, suggesting selective targeting of active ADAM10 in the tumour." (PMID 35804938, 2022). "The expression levels of Ki-67 and EpCAM were retained in CRC PDOs, whereas MUC2, a differentiation marker, was not expressed in either the original tumor or PDOs." (PMID 35379798, 2022). "Biodistributions of EpCAM-negative U937 and positive MDA-MB-231 tumors at 24 h confirmed tumor specific uptake with 0.75 and 2.4% ID/g, respectively." (PMID 35673581, 2022). "Based on the canonical marker gene expression, 3,085 cells were annotated as tumor cells (GPC3, EPCAM, AFP, ALB, DLK1), while 18,365 cells were designed as non-tumor cells." (PMID 35860547, 2022). "The engineering of ROR1-CAR-T cells with synNotch receptors that are specific for EpCAM or B7-H3, expressed on ROR1+ tumor cells but not on ROR1+ stromal cells, can induce ROR1 expression selectively within the tumor, thus sparing normal tissues." (PMID 35795050, 2022). "The reverse enrichment strategy can not only effectively realize the separation of CTCs; moreover, CTCs whose EpCAM expression is down-regulated due to EMT, even non-epithelial tumor cells, can be enriched." (PMID 35646880, 2022). "Since EpCAM and EGFR act on epithelial cells, no expression of these proteins is found in LNs without tumor." (PMID 36581931, 2022). "IHC results of mice‐bearing tumor showed that sorafenib can downregulate CK19+, EpCAM+ cell population but not CD13+ cell." (PMID 35652264, 2022). "The PD/SQ-derived and FR/SQ tumor-derived CAFs expressed high levels of fibroblast mRNA markers (via QPCR analyses) αSMA, PDGFRα and FAP, but very little or no epithelial cell marker EPCAM." (PMID 35982950, 2022). "Nestin, KLF4, ALDH1, EPCAM as well as ABCG2 expression was incongruous, with no clear relation to the four different parental tumor groups." (PMID 33800955, 2021). "Meanwhile, in analyses of TGF-β expression in tumor models in vivo, the combination of the EpCAM CAR T cells and hsBCL9CT-24 exhibited the lowest level, significantly reduced compared to the group of EpCAM CAR T cells alone without hsBCL9CT-24 treatment." (PMID 34790117, 2021). "We designed an antibody cocktail of lineage markers (CD24, CD31, CD45.2, CD49f, EpCAM, TER-119 and LYVE-1) to exclude non-fibroblast cells from the single cell suspension of tumours analysed by flow cytometry (FCM)." (PMID 34016130, 2021). "mRNA levels of Ki-67, CD24, CD44, CD31, MENA, CD49, ECAD, PCAD, EpCAM, CDX2, CK6, CK7, CK13, were significantly decreased in tumour tissue relative to non-tumour tissue." (PMID 33906633, 2021).